RAI1 (retinoic acid induced 1)
Diseases named in the same sentence as RAI1 in open-access papers (continued):
Sharing a sentence is not in itself a finding about the gene and the disease.
esophageal cancer (2 papers, 2023). A primary or metastatic malignant neoplasm involving the esophagus. "RAI1 is expressed in various cell lines, tissues, and tumor cells, and functions as a tumor suppressor in esophageal cancer with a strong ability to predict patient survival." (PMID 37165041, 2023). "Formerly considered to be a transcriptional regulator of circadian clock components in neuronal tissue, a recent study found RAI1 to act as a tumor suppressor in esophageal cancer; prior to this finding, the functional role of RAI1 in tumors was unknown." (PMID 37444571, 2023).
Failure to thrive (2 papers, 2011 to 2019). Failure to thrive (FTT) refers to a child whose physical growth is substantially below the norm. "In addition, failure to thrive (FTT)/feeding issues were less frequent (3/5) in de novo RAI1 mutation cases compared to deletion cases (19/19)." (PMID 21857958, 2011). "While delays in growth (height/weight) in early childhood were previously recognized for de novo RAI1 mutation cases, the frequency of failure to thrive (FTT) and feeding issues in infancy has not been documented." (PMID 21857958, 2011).
fragile X syndrome (2 papers, 2015 to 2022). A genetic syndrome caused by mutations in the FMR1 gene which is responsible for the expression of the fragile X mental retardation 1 protein. "Cell line analysis of genes altered by haploinsufficiency of RAI1 found retinoid x receptor beta (RXRB) as one of the ten main genes up-regulated and also proposed an interrelatedness in phenotype with several diseases that included DiGeorge syndrome and fragile X syndrome." (PMID 24519454, 2015).
Insulin resistance (2 papers, 2014 to 2025). Increased resistance towards insulin, that is, diminished effectiveness of insulin in reducing blood glucose levels. "It is interesting that Rai1+/− mice have increased abdominal adiposity but do not manifest insulin resistance." (PMID 25127133, 2014).
ROHHAD Syndrome (2 papers, 2018). "In 2015, a novel mutation was detected in the RAI1 gene in a boy aged 11 years who presented with the clinical findings of ROHHAD syndrome and the authors suggested that the patient had an overlap syndrome with SMS." (PMID 29553042, 2018). "Recently, a mutation in the RAI1 gene has been identified in a morbidly obese child diagnosed with ROHHAD Syndrome." (PMID 29794985, 2018).
scoliosis (2 papers, 2011 to 2015). A congenital or acquired spinal deformity characterized by lateral curvature of the spine. "Scoliosis was seen in 3/5 de novo (M2377, M2719, M2754) cases, consistent with published frequencies for common deletion (40–70%) and RAI1 mutation (36%) cases." (PMID 21857958, 2011). "However, the exact mechanism how SMS induce scoliosis is unclear, the potential mechanisms in the pathogenesis of congenital scoliosis of SMS included RAI1 microdeletion and RAI1 gene point mutation." (PMID 25929900, 2015).
spinocerebellar ataxia type 2 (2 papers, 2010). A subtype of type I autosomal dominant cerebellar ataxia (ADCA type I) characterized by truncal ataxia, dysarthria, slowed saccades and less commonly ophthalmoparesis and chorea. "In this study the transcript of Ataxin 2, a protein mutated in spinocerebellar ataxia type 2 (SCA2), had a fold change of 1.24 by microarray analysis; certainly suggesting a link between its expression and the overexpression of Rai1." (PMID 21629438, 2010).
Williams-Beuren syndrome (2 papers, 2018). "For example, disruption of the transcription factors RAI1 and WSTF in xenopus (also disrupted in Williams-Beuren syndrome) negatively impacts proper NCC migration, recapitulating the human craniofacial defects associated with the syndromes." (PMID 29950181, 2018).
Abdominal obesity (1 paper, 2014). Excessive fat around the stomach and abdomen. "Previous studies have shown that a significant number of adolescent individuals with either a deletion or point mutation of RAI1 present predominantly with truncal-abdominal obesity or are in the 90th percentile or greater for weight." (PMID 25127133, 2014).
allergic rhinitis (1 paper, 2023). Inflammation of the nasal mucous membranes caused by an IgE-mediated response to external allergens. "An animal experiment in mice with allergic rhinitis showed that RAI1 could influence Th1/Th2 balance and regulate the release of IgE by plasma cells." (PMID 37303953, 2023).
amyotrophic lateral sclerosis (1 paper, 2025). Amyotrophic lateral sclerosis (ALS) is a neurodegenerative disease characterized by progressive muscular paralysis reflecting degeneration of motor neurons in the primary motor cortex, corticospinal tracts, brainstem and spinal cord. "Although recent studies have linked RAI1 to amyotrophic lateral sclerosis (Ref." (PMID 40437981, 2025).
astrocytoma (1 paper, 2024). "RAI1 may counteract viral infection by regulating immune reactions in astrocytoma cells." (PMID 38584840, 2024).
bladder cancer (1 paper, 2024). "Further studies are required to determine whether hypermethylation of TMEM101 and RAI1 could be used as biomarkers for the screen and diagnosis of endometrial and bladder cancer, respectively." (PMID 38336771, 2024).
coronary artery disease (1 paper, 2019). "The RAI1-PEMT-RASD1 region is a replicated, genome-wide significant locus for coronary artery disease (CAD)." (PMID 30958265, 2019).
Cowden syndrome (1 paper, 2020). "Variants in SHANK3 can accompany Phelan–McDermid syndrome; PTEN, Cowden syndrome; NSD1, Sotos syndrome; and RAI1, Smith–Magenis syndrome." (PMID 32477112, 2020).
deafness (1 paper, 2016). An inherited or acquired condition characterized by the complete loss of the ability to hear from one or both ears. "It is interesting to note that the RAI1 gene is absent in the candidate gene list for genes associated with nonsyndromic and syndromic HL whereas OTOF and SLC26A4 are known as deafness-related genes." (PMID 27082237, 2016).
diabetes (1 paper, 2019). "CDKAL1, RREB1, and PPARG were not significant in either arm of the diabetes stratified analysis, while RAI1 and SLC9B2 were significant in the non-diabetes group." (PMID 31451708, 2019).
embryonic carcinoma (1 paper, 2015). "The initial discovery of RAI1 came from study of the P19 mouse embryonic carcinoma cell line, showing that the expression of GT1, a splice variant of RAI1, was significantly up-regulated after treatment with retinoic acid to induce neuronal differentiation." (PMID 24519454, 2015).
Esotropia (1 paper, 2011). A form of strabismus with one or both eyes turned inward ('crossed') to a relatively severe degree, usually defined as 10 diopters or more. "Some ocular abnormalities, either strabismus (2/4), esotropia (3/4), or hyperopia (1/4), were present in all our de novo RAI1 cases; this frequency is higher than previously appreciated; and more consistent with common 17p11.2 deletion cases." (PMID 21857958, 2011).
Hearing impairment (1 paper, 2016). A decreased magnitude of the sensory perception of sound. "About 60–68% of all SMS patients (with deletions of chromosome 17p11.2 region or with mutations in RAI1) have at least some degree of hearing impairment, which can be conductive, sensorineural, or mixed in nature." (PMID 27082237, 2016).
Hypotonia (1 paper, 2011). Hypotonia is an abnormally low muscle tone (the amount of tension or resistance to movement in a muscle). "Hypotonia, frequent otitis media, ocular anomalies, dental anomalies, hoarse voice, and brachydactyly occurred in our de novo RAI1 cases with frequencies consistent with published 17p11.2 deletion cases." (PMID 21857958, 2011).
intellectual disability syndromes (1 paper, 2025). "Moreover, RAI1 expression levels were commonly reduced in several intellectual disability syndromes not directly associated with RAI1 mutations." (PMID 40724914, 2025).
medulloblastoma (1 paper, 2021). A malignant, invasive embryonal neoplasm arising from the cerebellum. "Incidentally, CAG repeats were recently associated with three genes potentially involved in medulloblastoma: RAI1, BCL6B, and TNS1." (PMID 33765058, 2021).
mental disorder (1 paper, 2016). A disease that has its basis in the disruption of mental process. "The observation that a significant portion of RAI1 mRNA expression is genetically controlled raises the possibility that common RAI1 5′-region regulatory variants contribute more generally to psychiatric disorders." (PMID 26743651, 2016).
pancreatic ductal adenocarcinoma (1 paper, 2024). An infiltrating adenocarcinoma that arises from the epithelial cells of the pancreas. "For instance, cg25927164 (RAI1) and cg16561543 (BRF1) were hypermethylated in muscle-invasive bladder cancer and pancreatic ductal adenocarcinoma, respectively." (PMID 38336771, 2024).
promyelocytic leukemia (1 paper, 2019). "For the first time in 1997, rai1 was reported as a retinoic acid induced gene of acute promyelocytic leukemia cell." (PMID 31018489, 2019).
Seizure (1 paper, 2025). A seizure is an intermittent abnormality of nervous system physiology characterized by a transient occurrence of signs and/or symptoms due to abnormal excessive or synchronous neuronal activity in the brain. "Besides these phenotypic studies of animal models, the mechanisms underlying Rai1 regulation of weight abnormalities, disrupted sleep rhythms and epileptic seizures have been investigated." (PMID 40437981, 2025).
Spina bifida occulta (1 paper, 2011). The closed form of spina bifida with incomplete closure of a vertebral body with intact overlying skin. "It is of interest to note that a spina bifida occulta (SBO) variant occurred in one de novo (M2377) and one familial (M2826) case, both with RAI1 levels <50%." (PMID 21857958, 2011).
neurodevelopmental disorder (10 papers, 2018 to 2025). A behavioral and cognitive disorder with onset during the developmental period that involves impaired or aberrant development of intellectual, motor, or social functions. "The dysregulation of these mechanisms, particularly through mutations in RAI1, provides valuable insights into the molecular basis of neurodevelopmental disorders such as SMS." (PMID 40724914, 2025). "SMS and PTLS are two rare and distinct neurodevelopmental disorders caused by deletion and duplication of the dosage-sensitive gene RAI1, respectively." (PMID 35821519, 2022). "Smith–Magenis syndrome (SMS; OMIM #182290) and Potocki–Lupski syndrome (PTLS; OMIM #610883) are rare neurodevelopmental disorders that underscore the critical role of dosage-sensitivity in the RAI1 gene in determining distinct clinical outcomes." (PMID 40724914, 2025). "RA administration stimulates expression of RAI1, while decreased function of RAI1 has been described to contribute to multiple neurodevelopmental disorders." (PMID 41149794, 2025). "The newly created Rai1 KO Nile grass rat line using i-GONAD is a unique model for understanding the role of Rai1 in the neurodevelopmental disorder SMS." (PMID 38956550, 2024).
cancer (6 papers, 2011 to 2025). A tumor composed of atypical neoplastic, often pleomorphic cells that invade other tissues. "It is of interest though that the original identification of the endogenous RAI1 gene, in the mouse P19 embryonic carcinoma cell line, also described the protein to be present in the cytoplasm of neurons of the adult mouse brain and thus a cytoplasmic role was proposed." (PMID 24519454, 2015). "In addition, we sought to test the differential expression of RAI1 and TOM1L2 genes that were also located in the ±25 kb flanking region of this CpG and had valid gene expression information in both cancer datasets." (PMID 35710732, 2022). "However, in the COSMIC database, RAI1 it not a known cancer-related gene." (PMID 38310436, 2023).
genetic disorder (6 papers, 2021 to 2024). "Smith–Magenis syndrome (SMS; OMIM 182290) is a rare genetic disorder that results from an interstitial deletion of 17p11.2 and, in rare cases, from a retinoic acid induced 1 (RAI1) gene variant." (PMID 34316024, 2021).
tumor (5 papers, 2015 to 2025). "Just one single variant showed the required genotype composition in leukocyte and tumor DNA, a frameshift mutation in the gene RAI1." (PMID 25537509, 2015). "A few years later, in 1995, RAI1 was recognized as a key regulator of neural and glial cell development in a mouse model of an embryonic tumor cell line following exposure to high levels of retinoic acid." (PMID 40724914, 2025). "RAI1 (initially named Gt1) was first discovered as a gene activated in the mouse embryonic tumor cell line P19 by retinoic acid, a treatment that induces the cells to develop into neuronal and glial cells." (PMID 40724914, 2025).
neurological diseases (3 papers, 2021 to 2024). "Recent studies have implicated GLS, RAI1, GIPC1, MED15, EP400, MEF2A, and CNKSR2 in neurological diseases, with GLS, GIPC1, MED15, RAI1, and MEF2A sharing the same repeat loci reported in this study." (PMID 38871700, 2024). "The regions of the 3 CNVs are located in chromosome Xp22.31, 15q11.2–13.1 and 17p11.2, and harbored genes associated with neurological diseases including GABRB3, UBE3A, MAGEL2, RAI1, ALDH3A2, ATPAF2 according to the database of Online Mendelian Inheritance in Man (OMIM)." (PMID 33753861, 2021).
brain disorder (1 paper, 2024). A disease affecting the brain or part of the brain. "Based on these observations, it is plausible that modest changes in RAI1 expression also contribute alone or in combination with other genes to ASD and other brain disorders." (PMID 38674394, 2024).
RAI1 also shares sentences with these, for which no sentence is quoted: bipolar disorder (4 papers); developmental delay (4); autism spectrum disorder (3); breast carcinoma (2); advanced sleep phase syndrome (1); Ataxia (1); BrachyDactyly-Mental Retardation syndrome (1); cerebellar ataxia (1); colorectal cancer (1); DiGeorge syndrome (1); esophageal squamous cell carcinoma (1); glioma (1); head and neck squamous cell carcinoma (1); Huntington disease (1); Hypercholesterolemia (1); Hyperinsulinemia (1); hyperlipidemia (1); hyperopia (1); Kabuki syndrome (1); Koolen-de Vries syndrome (1); memory impairment (1); mental retardation, X-linked syndromic, Lubs type (1); microcephaly (1); morbid obesity (1); narcolepsy (1); Nonsyndromic Hearing Loss (1); obsessive-compulsive disorder (1); otitis media (1); overlap syndrome (1); pancreatic cancer (1).
A further 9 diseases each share a sentence with RAI1 in 1 paper.